DCN (decorin)
Diseases named in the same sentence as DCN in open-access papers (continued):
Sharing a sentence is not in itself a finding about the gene and the disease.
colorectal cancer (15 papers, 2009 to 2024). A primary or metastatic malignant neoplasm that affects the colon or rectum. "Several research groups have discovered that DCN deficiency promotes epithelial-mesenchymal transition and hepatic metastasis of colorectal carcinoma." (PMID 37464382, 2023). "Remarkably, CM of all colorectal cancer cell lines caused increased decorin expression, but presently we cannot explain this differential regulation." (PMID 25593993, 2014). "In this study, we synergistically combine NK cells with an oncolytic adenovirus carrying Decorin (rAd.DCN) for the treatment of colorectal cancer (CRC) in a xenograft mouse model." (PMID 39482550, 2024). "Here, we elucidated the functional role of B. adolescentis and its possible mechanism on the manipulation of Decorin+ macrophages in colorectal cancer." (PMID 37464382, 2023). "DCN is considered a marker for one of these subgroups in CAFs of colorectal cancer and high-grade serous ovarian cancer samples." (PMID 37963845, 2023). "Increased decorin expression has also been shown to attenuate the migration of colorectal cancer cells and promote apoptosis." (PMID 35777025, 2022). "Recombinant DCN, in combination with celecoxib, potentially suppresses epithelial-mesenchymal transition in colorectal cancer." (PMID 33809195, 2021). "Decorin effectively inhibited adhesion of both breast and colorectal cancer cells, although this was counteracted by type I collagen." (PMID 25593993, 2014). "In a model of colorectal cancer, Decorin was reported to interact with and stabilise E-cadherin, thereby attenuating the progression of colorectal cancer." (PMID 22880013, 2012). "Moreover, treatment with a combination of Celecoxib and DCN markedly inhibits EMT and proliferation of colorectal cancer cells in DCN−/− mice and it is proposed as a potential adjuvant protein therapy." (PMID 36358747, 2022). "We speculate that TGF-β1-induced decorin downregulation is counteracted by another, presently unknown, ligand in colorectal cancer CM." (PMID 25593993, 2014). "The aim of our study was to analyse the expression of DCN and its potential regulatory ncRNAs in metastatic colorectal carcinoma (CRC)." (PMID 35052821, 2022). "The expression of DCN was also shown in some studies to be reduced in colorectal carcinoma (CRC); however, we and others reported a higher expression of DCN in CRC." (PMID 35052821, 2022). "Therefore, decorin as “a guardian from the matrix” may be an invaluable tool in combatting colorectal cancer." (PMID 32824864, 2020). "However, DCN is a tumor suppressor gene in colorectal cancer." (PMID 28567416, 2017). "Overexpressed decorin reduced the activity of multiple receptor tyrosine kinases (RTKs) including the epidermal growth factor receptor (EGFR), an important player in colorectal cancer (CRC) pathogenesis." (PMID 32824864, 2020).
glioblastoma (14 papers, 2014 to 2024). The most malignant astrocytic tumor (WHO grade IV). "Increased ADC on DWI of patients with glioblastoma is associated with increased RNA and protein expression of DCN, a proteoglycan that modulates the ECM and has well established anti-angiogenic properties." (PMID 32908231, 2020). "Expression of decorin is recently reported to be seen in the tumor cell such as glioblastoma and is negatively associated with the overall survival rate of patients with glioblastoma multiforme." (PMID 32231160, 2020). "The DCN+/LUM+ CSC-like glioblastoma and neuroblastoma cells form secondary neurospheres when cultured in anchorage-independent conditions, and present a quiescent, less proliferative phenotype and temozolomide resistance." (PMID 36358747, 2022). "Glioblastoma and neuroblastoma cells increase the mRNA and protein levels of DCN and LUM when cultured under CSC enrichment conditions." (PMID 36358747, 2022). "We identified a negative association between DCN and VEGF-A and a positive association between DCN and VEGFR 1 & 2 and localize VEGFR 1 & 2 to the similar areas of microvascular proliferation in glioblastoma specimens." (PMID 32908231, 2020). "In the current study, we explore the association between DCN gene expression and diffusion MRI measurements in two large independent cohorts of GBM patients from The Cancer Genome Atlas (TCGA) and IVY Glioblastoma Atlas Project (IVY GAP)." (PMID 32908231, 2020). "The IVY Glioblastoma Atlas Project Database was used to evaluate DCN localization and relationship with VEGF pathway via in situ hybridization maps and RNA sequencing data." (PMID 32908231, 2020). "These associations are in concordance with DCN anti-angiogenic mechanisms in non-glioblastoma tumors, where DCN has been noted to bind to VEGFR120 and inhibit production of VEGF78." (PMID 32908231, 2020). "DCN localizes in glioblastoma specimens to areas of microvascular proliferation, the tunica adventitia of blood vessels within the tumor, and co-localizes to areas of VEGFR." (PMID 32908231, 2020). "Glioblastoma and neuroblastoma CSCs produce high levels of lumican and decorin to acquire temozolomide resistance and a quiescent phenotype." (PMID 31334229, 2019). "Since decorin has been shown to have a differentiation effect on other types of human cancer cells, we hypothesized that decorin also has a differentiation effect on glioblastoma cells." (PMID 24625664, 2014). "Clearly, cells expressing IRE1α RNase mutants heightened the expression of ECM markers characteristic of glioblastoma malignancy or invasion, including fibrillar collagens, the collagen cross-linker LOX and the proteins THBS1, YKL-40, DCN and LAMA4." (PMID 26325176, 2015). "Collagen VI, a promoter of tumorigenesis and a supporter of stem cell niches, also functions as an autophagy inducer in skeletal muscle stem cells by functionally interacting with decorin, a small leucin-rich proteoglycans (SLRP) that has been shown to induce stemness in glioblastoma." (PMID 31334229, 2019).
atherosclerosis (13 papers, 2013 to 2025). A disease characterized by the build-up of fatty material and calcium deposition in the arterial wall resulting in partial or complete occlusion of the arterial lumen. "Because of its anti-inflammatory, anti-oxidative, and anti-fibrotic effects, decorin can be linked to vascular health and diseases, such as AS and atherosclerosis, which are common in patients with ESRD." (PMID 40283096, 2025). "The aim of the present study was to clarify the association between lipid metabolism and the atherosclerosis in early-stage chronic renal failure at the molecular level and to explore the efficacy of decorin on chronic renal failure." (PMID 25574240, 2015). "In addition to AS, atherosclerosis can be linked to decorin in patients undergoing chronic PD." (PMID 40283096, 2025). "This lipid retention occurs primarily in the deep intima based on the charge-charge interaction between apoB and biglycan and decorin secreted in high amounts by SMCs in this region, and prior to any significant monocyte infiltration in human atherosclerosis." (PMID 35795646, 2022). "On the contrary, other authors concluded that systemic overexpression of decorin reduced inflammation and fibrosis in the atherosclerotic plaques of atherosclerosis-prone mice and slowed disease progression." (PMID 35211520, 2022). "It is therefore highly likely that DCN's role in atherosclerosis is cell specific, as shown recently, in the human heart." (PMID 28757161, 2017). "Nevertheless, in contrast with lumican and decorin, the evidence about the involvement of prolargin in either atherosclerosis or AS is very limited." (PMID 26620461, 2015). "Systemic over-expression of decorin was previously reported to reduce macrophage infiltration and gelatinase activity in a mouse model of atherosclerosis." (PMID 25781946, 2015). "Previous work also showed that decorin overexpression reduced atherosclerosis development in ApoE KO mice, supporting a protective role for decorin in vascular diseases." (PMID 24205352, 2013). "It had been verified in ApoE (−/−) mice that the over expression of DCN could reduce inflammation in atherosclerotic plaques, thereby decelerating the progression of atherosclerosis." (PMID 37089432, 2023). "Decorin overexpression reduces atherosclerosis in ApoE KO mice." (PMID 28757161, 2017). "DCN is a small leucine-rich proteoglycan that plays important roles in atherosclerosis." (PMID 28757161, 2017). "Thus, modulation of SPARC production may have potential implications for postinfarction healing, and decorin has a protective role in several cardiac diseases, including atherosclerosis, hypertrophy, and myocardial infarction." (PMID 37533033, 2023).
diabetes (13 papers, 2012 to 2025). "Given the prominence of decorin, we sought to interrogate its association with complications in human diabetes." (PMID 38305779, 2024). "Diabetes was induced through intraperitoneal injection with streptozotocin combined with a high-fat diet, and decorin was overexpressed via recombinant adeno-associated virus in Wistar rats." (PMID 28290552, 2017). "In fact, in our study, decorin was also associated with the presence of diabetes mellitus." (PMID 35211520, 2022). "It meant that overexpression of DCN attenuated diabetes-induced myocardial fibrosis by inhibition of TGFβ1 pathway." (PMID 33365011, 2020). "The internal dimension of the left ventricle (LVID) was increased in the diabetes group and ameliorated by overexpression of decorin." (PMID 28290552, 2017). "Previous work suggests that decorin might be produced in response to diabetes, potentially as a moderator or dampener of fibrosis." (PMID 38305779, 2024). "We investigated that whether DCN play the protective role in diabetes not only through reduction of TGF-β1 but also by suppressing NF-κB." (PMID 33365011, 2020). "The absence of major effects of decorin deficiency in our study may reflect compensatory mechanisms, and potential phenotypes may be more evident in models of greater homeostatic stress, such as diabetes or muscle injury." (PMID 40616270, 2025). "Decorin and PEDF both have protective effects against diabetes complications in multiple organs and tissues, including retinopathy, nephropathy, and cardiac diseases." (PMID 37816033, 2023). "This duality of effect of diabetes as a suppressor of VEGF and an inducer of TSP1 is reminiscent of those reported previously in aged animals and in decorin-overexpressed cultured endothelial cells." (PMID 30720765, 2019). "This duality of effect of diabetes as a suppressor of VEGF and an inducer of TSPs is reminiscent of those reported previously in aged animals and in cultured endothelial cells overexpressing decorin." (PMID 25381014, 2015).
hepatoma (11 papers, 2016 to 2026). "It has been previously shown that CAFs promote vascular invasion of hepatocellular carcinoma through DCN downregulation." (PMID 38667295, 2024). "Specifically, it is considered that decorin suppresses the proliferation rates and metastatic potential of multiple types of cancer cells, such as hepatocellular carcinoma, breast cancer, and non-small-cell-lung cancer." (PMID 35454797, 2022). "We studied whether our recently constructed decorin-expressing herpes simplex virus (HSV) vector can reduce angiogenesis in xenografted liver carcinoma cells in the chorioallantoic membrane model." (PMID 42015278, 2026). "The expression of DCN in hepatocellular carcinoma tissues was significantly lower than in normal tissues, suggesting that DCN may have inhibitory effects on the invasion and metastasis of cancer cells." (PMID 40109852, 2025). "Indeed, TGFβ1 is a known transcriptional inhibitor of DCN gene, and the hepatoma cell lines applied produce considerable amounts of the cytokine." (PMID 32477937, 2020). "In addition, applying conditioned media of hepatoma cells inhibited decorin expression in LX2 stellate cells in vitro." (PMID 32477937, 2020). "Similarly, in our earlier experiments we found that addition of human recombinant decorin to the Hep3B hepatoma cell line provoked activation of IGF-1R and insulin receptors and massive Akt activation." (PMID 32477937, 2020). "Specific extracellular matrix proteoglycans, such as versican, aggrecan, biglycan, and decorin, which are increased in rat hepatocellular carcinomas, may affect binding with the C4S attachments on the proteoglycan." (PMID 27078017, 2016). "Earlier we found that the CM of hepatoma cells inhibited decorin production of the LX2 stellate cell line; here we show evidence that tumor cells of a different tissue origin can also suppress decorin production by liver fibroblasts." (PMID 32824864, 2020).
ovarian carcinoma (11 papers, 2011 to 2025). A malignant neoplasm originating from the surface ovarian epithelium. "Moreover, the DCN (Decorin) gene encodes a member of the small leucine-rich proteoglycan family of proteins acting as a tumor suppressor gene lowly expressed in colon, breast, gastric, and ovarian cancer cells." (PMID 28567416, 2017). "Literature reports have demonstrated that reduced concentrations of decorin measured in ovarian cancer cells and tumour stroma correlated with histological malignancy, higher clinical stage (according to FIGO) and risk of metastasis." (PMID 41463127, 2025). "A study showed that the administration of exogenous decorin to ovarian cancer cell cultures reduced their proliferation and ability to colonise." (PMID 41463127, 2025). "Of special attention is the description of the expression levels of genes such as POSTN, CHI3L1, CAV-1, IRS1, DCN, which according to literature data are associated with diseases such as POI, PCOS, and ovarian cancer." (PMID 34827207, 2021). "Theexpression of both decorin and lumican is altered in various cancers, includingserous epithelial ovarian cancer." (PMID 21637745, 2011). "Ovarian cancer patients with higher RNA levels of TPH2, DCN, TRHDE, and LUM have lower OS when compared with ovarian cancer patients with lower levels of these genes." (PMID 35008958, 2022). "Following RBPMS knockout, the expression levels of TPH2, DCN, TRHD2, LUM, and SERPINE1 were in agreement with the survival outcomes: The PFS and OS were worse in ovarian cancer patients with higher levels of these transcripts." (PMID 35008958, 2022). "DCN (Decorin), AKT3 (AKT Serine/Threonine Kinase 3), and TIMP2 (tissue inhibitor of metalloproteinases 2) are the other novel candidate target genes for miR-182 involved in the regulation of ovarian cancer biological processes." (PMID 34721577, 2021). "We could not confirm the associations of SNPs in two stromal genes,DCN and LUM, with the risk of serousepithelial ovarian cancer, the most common histological type of ovarian cancer,using a multi-stage replication approach within the OCAC." (PMID 21637745, 2011).
squamous cell carcinoma (11 papers, 2011 to 2025). A carcinoma arising from squamous epithelial cells. "Several studies confirm that reduced expression of decorin in tumor stroma is associated with poor prognosis in metastatic invasive breast cancer and complete absence promotes the progression of several tumor types, including urothelial carcinoma, squamous cell carcinoma, and myeloma." (PMID 40542654, 2025). "It was also shown that decorin gene is under-expressed by at least 50% in lung adenocarcinomas and squamous cell carcinomas compared to normal tissue." (PMID 32477937, 2020). "Our findings are in line with a vast number of earlier studies, where delivery of decorin via an adenovirus vector into the tumor cells inhibited the growth of lung, colon, and squamous cell carcinomas by attenuating EGFR phosphorylation." (PMID 32477937, 2020). "Early studies utilizing virus-mediated gene therapy showed DCN transduced into tumor cells inhibited the growth of lung, colon, and squamous cell carcinomas in vivo." (PMID 26697491, 2015). "Earlier, it has been shown in mice that decorin gene delivery decreases the proliferative index and alters the architecture and differentiation of the tumor xenografts, thereby retarding the growth of colon and squamous cell carcinomas." (PMID 23007289, 2013). "Systemic delivery of decorin protein core, downregulated the epidermal growth factor receptor (EGFR), leading to growth inhibition as well as increased apoptosis of squamous cell carcinoma xenografts in mice." (PMID 24499526, 2013). "Previously; we have shown that decorin is aberrantly expressed as well as translocated to the nucleus in dysplastic oral keratinocytes (DOK) and malignant squamous cell carcinoma (SCC-25) and in oral cancer biopsy tissue." (PMID 21958730, 2011). "Previously; we have shown that decorin is aberrantly expressed in the nucleus in human dysplastic oral keratinocytes (DOK) and malignant squamous cells carcinoma (SCC-25) and human biopsy tissues." (PMID 21958730, 2011). "Aberrant expression of decorin (DCN) in dysplastic and squamous carcinoma oral epithelial cells, but absent in normal mucosa tissue, has been reported suggesting its role as a possible biological marker of imminent progression." (PMID 33889206, 2021). "Previously, we have shown that multifunctional proteoglycan decorin is aberrantly expressed and localized in the nucleus bound to nuclear epidermal growth factor receptor (EGFR) in human dysplastic oral keratinocytes (DOK) and malignant squamous carcinoma cells (SCC-25)." (PMID 22507529, 2012).
congenital stromal corneal dystrophy (10 papers, 2015 to 2024). Congenital stromal corneal dystrophy (CSCD) is an extremely rare form of stromal corneal dystrophy characterized by opaque flaky or feathery clouding of the corneal stroma, and moderate to severe visual loss. "A genetic mutation at this position in the Decorin (DCN) gene (Class I SLRP) leading to a truncated DCN protein core has been found in human congenital stromal corneal dystrophy." (PMID 34638928, 2021). "In the cornea, decorin is abundantly expressed in the stroma and accumulation of a truncated form of decorin causes stromal opacity in congenital stromal corneal dystrophy." (PMID 32903857, 2020). "Interestingly, SPARCL1 stimulates the expression of decorin, a known gene behind congenital stromal corneal dystrophy (CSCD), making this gene functionally a plausible cause for the new dystrophy." (PMID 39394466, 2024). "In humans, mutations in the decorin gene could cause congenital stromal corneal dystrophy (CSCD) when truncated decorin binds to collagen, resulting in aggregation in the stroma." (PMID 36611867, 2022). "Congenital stromal corneal dystrophy (CSCD) is associated with mutations in the Decorin gene (DCN)." (PMID 26828927, 2016). "There have not been any mutations reported for DCN in human malignancies, whereas such mutations cause human disease called congenital stromal corneal dystrophy (CSCD), the disease characterized by corneal opacities and vision impairment." (PMID 26697491, 2015). "The role of Decorin in organising the extracellular matrix was examined in normal human corneas and in corneas from patients with Congenital Stromal Corneal Dystrophy (CSCD)." (PMID 26828927, 2016). "For the CCT loci identified here, DCN (12 kb from rs7308752) and KERA in the same locus (75 kb from rs7308752), are involved in congenital stromal corneal dystrophy (OMIM: 610048) and Cornea plana 2 (OMIM:217300), respectively." (PMID 29760442, 2018).